CCR1 (C-C motif chemokine receptor 1)
Diseases named in the same sentence as CCR1 in open-access papers (continued):
Sharing a sentence is not in itself a finding about the gene and the disease.
tumor (continued). "To investigate the mechanism by which CCL15-CCR1 axis promotes ESCC progression, we conducted a tumor-related gene PCR array analysis in EC109 cells following CCL15 and CCR1 knockdown." (PMID 40740234, 2025). "Both CCR1 and CCL15 were markedly overexpressed in ESCC tissues compared to adjacent non-tumor tissues." (PMID 40740234, 2025). "Recent studies on tumor-derived EVs show they can modulate gene expression in endothelial cells, promoting VEGF, VWF, VEGFR2, CXCL5, and CCR1 expression and enhancing endothelial cell proliferation and migration." (PMID 40141288, 2025). "Subsequently, we investigated the correlation between CCR1, CCR5, and CCR7 and the degree of immune cell infiltration in the tumor microenvironment." (PMID 38552222, 2024). "In the context of OAC, CCR1, CCR5, and CX3CR1 were identified as key drivers of erroneous T cell migration to the omentum at the expense of effective anti-tumour immunity." (PMID 38672174, 2024). "Further, we found that myeloid cells positive for both CCR1 and CXCR2 were accumulated around the tip of the tumor in human clinical CRC specimens." (PMID 38750114, 2024). "Immature myeloid cells (iMCs) are recruited from the bone marrow to the tumor invasion front express matrix metalloproteinases MMP9, MMP2, and CCR1, migrating toward the Ccl9 expressed by the tumor epithelium in adenocarcinoma." (PMID 39768150, 2024). "CCL8 is a monocyte chemokine that can interact with CCR1, CCR2B, and CCR3; it also regulates tumor occurrence, antiviral infections, and inflammatory immunity in the host." (PMID 39185422, 2024). "Several studies have also shown that the recruitment of CCR1+ myeloid cells via CCR1 ligands, such as CCL2, CCL9 and CCL15, promotes invasion, metastasis, and angiogenesis in CRC and other tumor types." (PMID 38750114, 2024). "In this study, we focused our investigation on the CCR1, CX3CR1, and CCR5 chemokine pathways, which have important roles in anti-tumour T cell biology." (PMID 38672174, 2024). "Further experiments should be performed, including the injection of anti-CCR1 antibody, or the addition of CCL9 after splenectomy, to further confirm the effect of CCL9 in tumor immunity." (PMID 38046278, 2023). "Recently, a therapeutic approach by in vivo silencing of CCR1 and CCR5 on myeloid cells has shown to strongly inhibit tumour progression by converting PMN-MDSCs into anti-tumour neutrophils." (PMID 36161514, 2023). "The antagonist of CCR1, CCX721, also reduces tumor burden and osteolysis in a mouse model of myeloma bone disease." (PMID 36173487, 2023). "These upregulated chemokines in GBM, such as C-C chemokine receptor type 1 (CCR1) and interleukin (IL-1b) are the direct targets of 181d tumor-suppressing activity." (PMID 37371047, 2023). "The mechanisms of the disease progression included CCL15-mediated autocrine stimulation of the tumor invasion and recruitment of CCR1+ cells, of which 80% were CD14+ monocytes inducing activity of pro-tumor factors and accelerating metastasis." (PMID 37185750, 2023). "In tumor-infiltrating macrophages we also observed increased activation of cytokine-responsive genes IFITM3, CCR1 and UBB (FDR=10-4), as well as upregulation of genes involved in MHC Class II presentation H2-Aa, H2-Ab1, H2-Eb1 and CD74 (FDR=0.0015)." (PMID 36911698, 2023). "CCR1, CCR2B, CCR3, and CCR5 are receptors for CCL8 that are expressed in both immune and tumor cells and play pro-cancer and anti-cancer roles." (PMID 38136340, 2023). "4PD-mediated in vivo silencing of CCR1 and CCR5 on myeloid cells and myeloid precursors was necessary and sufficient to inhibit tumor progression." (PMID 35064009, 2022). "This antibody that depletes PMN but leaves untouched T and NK subsets significantly reduced the therapeutic effects of CCR1 and CCR5 shRNAs but inhibited tumor progression in mice treated with the scrambled shRNAs." (PMID 35064009, 2022).
tumor (continued). "Our data support the notion that CCR1 and CCR5 and their ligands are a master immunological hub activated by several tumor derived factors." (PMID 35064009, 2022). "It is also worth investigating which ligands CCL8 binds to, including CCR1, CCR2, CCR3, and CCR5, and thus how it affects the downstream signaling pathways that lead to changes in the biological behavior of tumor cells." (PMID 36072582, 2022). "Some receptors like chemokine (C-X-C motif) receptor 4 (CXCR4) and C-C chemokine receptor type-1 (CCR-1) have successfully been modified on the MSC surface for better inflammation and tumor site tracking." (PMID 36660431, 2022). "While silencing of either CCR1 or CCR5 gave modest results, silencing both receptors significantly (p<0.001) reduced tumor size." (PMID 35064009, 2022). "In mice treated with the isotype control, CCR1 and CCR5 targeted silencing significantly reduced tumor progression compared with the PBS control." (PMID 35064009, 2022). "In all these models, chronic targeted silencing of CCR1 and CCR5 significantly reduced tumor growth and the lung metastases in the 4T1 model." (PMID 35064009, 2022). "Once the capacity of 4PD to bind and transfect myeloid cells in vivo with multiple shRNAs was determined, we evaluated the effect of chronic CCR1, CCR2, CCR5, and CCR7 silencing on tumor progression." (PMID 35064009, 2022). "To understand if CCR1 and CCR5 blockade modulates not only the phenotype but also the function of myeloid cells induced by tumor derived factors, we employed bone marrow cells from naïve mice." (PMID 35064009, 2022). "As observed above, CCR1 and CCR5 targeted silencing significantly inhibited tumor growth in BALB/c mice." (PMID 35064009, 2022). "Instead, we found that the simultaneous inhibition of CCR1 and CCR5 prevents MDSC differentiation driven by tumor derived factors or recombinant cytokines and promotes the generation of neutrophils with a strong antitumor activity." (PMID 35064009, 2022). "We used the 4PD nanoparticle for the in vivo targeted silencing of CCR1, CCR2, CCR5, and/or CCR7 in the myeloid cells of tumor bearing mice to evaluate the effect of treatments on tumor growth, myeloid cell trafficking and polarization." (PMID 35064009, 2022). "The results of necroptosis influences on the tumor immune microenvironment showed that significantly up-regulated expression levels of chemokines existed in Clusters B and C, such as CCL11, CCR1, CXCL10, and PPBP (upper part)." (PMID 35911707, 2022). "Transcriptome functional and cytokine analysis indicated that tumor derived factors induced CCL3 and CCL4 in HSPCs that, through the autocrine engagement of CCR1 and CCR5, induced HSPCs differentiation in MDSCs." (PMID 35064009, 2022). "Based on Oncomine database, we identified that expression of CCR1, CD3D, MAZ, PHLDA1, and RASD1 was higher in tumor than that in normal tissue at the pan-cancer level." (PMID 36092920, 2022). "Since CCR1 and CCR5 targeted silencing mediates a significant antitumor effect, we evaluated its action on the tumor microenvironment." (PMID 35064009, 2022). "Chemokine CCL5 participates in the proliferation and migration of tumor cells, as well as angiogenesis and lymphangiogenesis, by binding to receptors CCR5, CCR3 and CCR1." (PMID 36514094, 2022). "The transcriptome analysis also revealed that tumor derived factors induced bone marrow cells to transcribe CCL3, CCL4, and other ligands of CCR1 and CCR5." (PMID 35064009, 2022). "Loss of SMAD4 promotes expression of CCL15 by CRC and recruitment of CCR1+ TANs (CCL15-CCR1 axis) with both arginase-1 (ARG-1) and matrix metalloprotease 9 (MMP-9) activity, forming a premetastatic niche for the disseminated tumor cells —e.g., in the lungs." (PMID 33917620, 2021). "A selective CCR1 antagonist, CCX721, was able to decrease tumor burden and osteolytic lesions in murine models of multiple myeloma (MM) bone disease, through the blockade of osteoclasts." (PMID 34575965, 2021).
tumor (continued). "Proinflammatory chemokine CCL5 triggers key mechanisms such as EMT, angiogenesis, and metastasis and binds with CCR1, CCR3, and CCR5 which are present on the surface of myeloid cells, T cells, and tumor cells." (PMID 34220337, 2021). "In mice, circulating cDC precursors (pre-cDCs) expressing the chemokine receptors CCR1 and CCR5 migrate into the tumor site through attraction to CCL3, which is produced by tumor cells." (PMID 34572844, 2021). "CCL5 and its receptors CCR1 and CCR5 are key players that induce microglia migration to the tumour site and subsequent changes in phenotype." (PMID 33803414, 2021). "CAR-T cells commonly express receptors RANTES receptors, such as CCR1, CCR3, and CCR5, and combined use of CCL5-expressing oncolytic virus with engineered CAR T cells powerfully promoted the viability and tumor clearance in some of the preclinical studies." (PMID 33494834, 2021). "CC- and CXC chemokine receptors such as CCR1, CCR4, CCR7, CCR9, CCR10, CXCR1–5, and CXCR7 exhibit overexpression in a tumor cell response to proinflammatory cytokines." (PMID 34220337, 2021). "This is particularly relevant since these cells also over-express CCR1 and CCR5, chemokine receptors for ligands secreted by tumor cells which are shared with monocytes/macrophages, dendriticcells, and neutrophils." (PMID 33076479, 2020). "In different transplantable tumor models, this process was shown to be largely driven by the tumor expression of CCL3, a ligand of CCR1 and CCR5, two chemokine receptors expressed by pre-cDCs." (PMID 32486257, 2020). "In fact, CXCR4, SPP1, ACKR3, CCL2, PTGS2, CD274 (PD-L1), CXCL11 were upregulated while CCL28, CCR1, CCR7 were down regulated in both comparisons (blue boxes), suggesting this as a signature specific of the core region of the tumor." (PMID 33066172, 2020). "Another therapeutic approach includes the use of a CCR1 antagonist, for example BL5923, which reduces the recruitment of immature myeloid cells into the tumor and inhibits liver metastasis in mice with colon cancer." (PMID 33182504, 2020). "Chemokine receptors CCR1 and CCR5 are expressed on monocytes and facilitate their recruitment under chemotactic gradient of CCL5 and CCL731 and play a crucial role in tumor progression." (PMID 30850664, 2019). "It is thus likely that blockade of MAM-recruiting chemokine receptors such as CCR1, CCR2, CCR5 has minimum effects on the tumor infiltration of CD8+ T and NK cells, which is indispensable for immunotherapy efficacy." (PMID 30483271, 2018). "Small molecule inhibitors BX471 and TAK779, which selectively inhibit CCR1 and CCR5, respectively, prevent OCL differentiation in vitro; however, only BX471 had a significant effect on 5TMM tumor burden and bone lesions in vivo." (PMID 29930538, 2018). "For example, tumor secrete ligands CCL5, CCL7, and CXCL8, bind to their receptors CCR1 or CXCR2 expressed on subtypes of MDSCs, and attract MDSCs in the tumor microenvironment." (PMID 29299180, 2017). "Herein, the increase of Ccl3, Ccr1 and Ccr5 in SCC mouse tumours is indicative of contribution of these molecules to oral carcinogenesis." (PMID 28881626, 2017). "The tumor-promoting effect of MSCs is attributed to the activation of epithelial–mesenchymal transition (EMT) process, which is mediated by CCL5/CCR1/β-catenin/Slug pathway." (PMID 28542126, 2017). "We further confirm expression of CCL5 receptors (CCR1 & CCR5) by EPCs, as well as significant tumor growth and angiogenesis defects in CCR5 null mice." (PMID 27863423, 2016). "Expression of the inflammatory chemokine receptors, CCR1, CCR2, CCR3, CCR5 and CX3CR1, was significantly enriched on both Foxp3+ and Foxp3− CD4+ T cells within the tumours when compared with spleens and lymph nodes." (PMID 25495686, 2015). "Previous studies have shown that myeloid-derived suppressor cells (MDSCs), tumor-infiltrating lymphocytes (TIL), MSCs, CAFs and CSLCs can produce CCL5 and that cancer cells express the CCL5 receptors CCR1, CCR3, and CCR5." (PMID 25788271, 2015).
tumor (continued). "Targeting MDSC expression of CCR2 led to the downregulation of other chemokine receptors in MDSC, such as CCR1, CCR5 and CXCR4, supporting the pivotal role of CCR2-CCL2 signaling in in vivo MDSC migration and tumor growth." (PMID 26462153, 2015). "CCR5 and CCR1 are mainly detected in T lymphocytes and monocytes but only low expression of CCR5 is detected in the tumor cells." (PMID 24523569, 2014). "CCL5 activates CCR1, -3 and -5, and CCL5 expression by tumour cells in patients with stage I lung adenocarcinoma has been associated with improved survival." (PMID 20429924, 2010). "ERBB2 and CCR1 were genes activated in late EECs, while APBA2 (MINT2) and CDK inhibitor p16 tumor suppressors in early EECs." (PMID 20015385, 2009). "Finally, in the CCL network, CCL3 and CCL3L3 produced by MG1, MG2, tumor-cell clusters 4 and 6, oligodendrocytes, and MDM5 engaged CCR1 on MG3, while CCL5—expressed exclusively by MDM5—also targeted MG3." (PMID 41503214, 2026). "LLC1.1 wt primary tumor growth was comparable in BL6 and Ccr1-/- mice to LLC1.1-Ccl2KD cells." (PMID 39566333, 2025). "Additionally, pro-inflammatory factors upregulate chemokine receptors such as CCR1, CCR4, and CXCR7, enabling tumor cells to metastasize to specific organs." (PMID 39981173, 2025). "Accordingly, tumor cell-derived supernatant induced monocyte recruitment of wt and Ccr1-/- monocytes, but not of Ccr2-/- monocytes, which is in agreement with previous studies." (PMID 39566333, 2025). "Similarly, CCR1 and ITGB7 contribute to critical tumor-stroma interactions that drive MM cell migration, adhesion, and drug resistance, emphasizing their therapeutic relevance." (PMID 40597436, 2025). "Given the inverse relationship between CCL23 and CXCL10 in human ovarian ascites samples and reduced survival in patients with low tumor CXCL10 expression, we hypothesized that the activation of CCR1 via CCL23 impairs CXCL10 secretion from myeloid cells." (PMID 41463176, 2025). "CD36 displayed strong positive correlations with immune receptors such as CCR1, CCR2, CCR4, CXCR1, and CXCR2, indicating its potential role in amplifying chemokine-receptor interactions and shaping immune cell trafficking within the tumor microenvironment." (PMID 41550652, 2025). "Although CCR1 and CXCR2 on myeloid cells could be involved in tumor progression, it remains elusive what effect would be observed if both of those are blocked." (PMID 38750114, 2024). "MDSCs have several chemokine receptors, including CCR1, CCR2, CCR3, CCR5, CCR12, CXCR2, CXCR4, and C5aR1.25In the current study, MDSCs may express CCR1, the receptor of CCL9, which mediated the migration of MDSCs to tumor tissue." (PMID 38046278, 2023). "Chemokines secreted by TAMs, including CCL3, CCL5, CCL15, CCL18, CXCL8 and CXCL12, promote tumor metastasis, angiogenesis, cancer cell survival, immunosuppression and resistance of cancer cells after chemotherapy via CCR1/5, CCR5, CCR1, CCR8, CXCR1/CXCR2, CXCR4, respectively." (PMID 36173487, 2023). "These iMCs displayed CCR1 expression enabling migration along with CCL9 gradient, as well as intense production of matrix metalloproteinases MMP9 and MMP2; therefore, the iMCs promoted tumor invasion." (PMID 37185750, 2023). "Direct contact between MDA-MB-231 tumor cells and ASCs or adipocytes in this model promoted the expression of C-C motif chemokine ligand 5 (CCL5) and specifically the corresponding receptor C-C chemokine receptor type 1 (CCR1)." (PMID 37444610, 2023). "CCR1 was highly expressed by monocytes and macrophages, CCR5 was highly expressed by T cells and monocytes, while PITPNM3 was highly expressed by epithelial/tumor cells." (PMID 36850011, 2023). "The observed increase in the abundance of CCR1, CCR4 and/or CCR5+CD8+ T cells may reflect an RT-induced T-cell response directed against NPC tissue, after which these T cells efflux from the tumor into the blood of responding patients." (PMID 36980772, 2023).
tumor (continued). "It is particularly noteworthy that 6 chemokine receptors in GO term “chemokine binding”, including CXCR4, CCR5, CCR1, CCRL2, CMKLR1 and A2M, are specific expressed in FGFR2+ fibrocytes before arriving in tumor sites suggesting their possible roles in fibrocyte recruitment." (PMID 35941662, 2022). "Using an agnostic nanoparticle-based strategy, we first discovered that the silencing of both CCR1 and CCR5 was necessary and sufficient to change the phenotype and function of tumor-infiltrating myeloid cells and restrain tumor progression in all mouse cancer types tested." (PMID 35064009, 2022). "In addition to mediating MDSCs migration, the CCR1 and CCR5 silenced in vivo can also lead to repolarization of MDSCs into tumor-killing neutrophils thus playing an anti-tumor effect." (PMID 36225938, 2022). "CCR1, CCR2 and CCR3 were reported to be potential receptors of CCL7 in tumor microenvironment." (PMID 35715847, 2022). "Having shown that CCR1 and CCR5 are required for tumor driven MDSC differentiation in mice, we next evaluated whether a similar pathway regulated tumor induced myelopoiesis in human." (PMID 35064009, 2022). "This argues against a role of CCR1 and CCR5 on myeloid cell trafficking to the tumor." (PMID 35064009, 2022). "We show that tumor derived factors prime hematopoietic stem and precursors cells (HSPCs) to secrete CCL3 and 4 that promote HSPC differentiation into protumoral MDSCs via CCR1 and CCR5 signaling." (PMID 35064009, 2022). "Taken together, these data suggest that targeted inhibition of CCR1 and CCR5 on myeloid cells alters the tumor microenvironment by reducing the number of PMN-MDSCs and M2 macrophages and by increasing the concentration of cells with a phenotype consistent with classical neutrophils." (PMID 35064009, 2022). "In summary, our data support a model by which cancer-driven protumoral myelopoiesis is regulated by a circuit in which tumor derived factors induce the production of CCL3 and CCL4 and other CCR1 and CCR5 ligands that, by engaging CCR1 and CCR5, autocrinally promote their differentiation into MDSCs." (PMID 35064009, 2022). "The expressions of CCR1, PNOC, and VIP genes were significantly correlated with tumor purity, B cell infiltration, CD8+T cell infiltration, CD4+T cell infiltration, macrophage infiltration, neutrophil infiltration and dendritic cell infiltration, and the differences were statistically significant." (PMID 35174205, 2022). "While tumor-infiltrating myeloid cells from control mice did not affect neoplastic cell number, CD11b+ cells from CCR1 and CCR5 shRNA treated mice drastically reduced the number of 4T1 cells in culture indicating a tumoricidal action." (PMID 35064009, 2022). "We identified multiple tumor-immune interactions, for example between CXCR3, CCL5, TNFRSF1B, and VCAM1-expressing malignant T cells and macrophages/fibroblasts positive for CXCL9, CCR1, GRN, and IGTB1, respectively." (PMID 33816243, 2021). "Indeed, it was found that primary cultures of microglia co-expressed CCR1 and CCR5, and hence either receptor is capable of trafficking GAMs to the tumour." (PMID 33803414, 2021). "Conversely, CCR1 and CCR10 were found upregulated in GBM infiltrating area compared to the tumor core, which suggests a role for these receptors at the margin of the tumor, probably linked to cell invasion or communication with the tumor microenvironment (TME)." (PMID 35008294, 2021). "CCL5 and CCR1/CCR3/CCR5 expression correlates with tumor invasiveness, since none of these molecules are expressed in ovarian precancerous tissues but all are expressed in primary cancer and metastatic tissues." (PMID 32630699, 2020). "The C-C chemokine receptor type 1 (CCR1) + cells have the characteristic of expressing and secreting matrix metalloproteinase 9 (MMP9), which is involved in tumor invasiveness by promoting tumor–stromal interactions." (PMID 32722068, 2020).